NECTIN1 (nectin cell adhesion molecule 1)
Diseases named in the same sentence as NECTIN1 in open-access papers (continued):
Sharing a sentence is not in itself a finding about the gene and the disease.
ductal carcinomas (2 papers, 2013 to 2023). "Expression of Nectin-1 and Nectin-2 was higher in ductal carcinomas than in all other histological types (Nectin-1: ductal 348+/−122 versus other 112+/−27, p = 0.063; Nectin-2: ductal 104+/−93 versus other 82+/−38, p = 0.0037)." (PMID 24386110, 2013).
encephalitis (2 papers, 2012 to 2024). An acute inflammatory process affecting the brain parenchyma. "Other viruses, such as HSV-2 and varicella zoster virus, which also partly use NECTIN-1 to enter cells, may cause encephalitis in TMEFF1-deficient patients." (PMID 39048830, 2024). "Experiments with mice lacking either nectin-1 or HVEM showed that nectin-1 is essential for HSV-1 infection via the intracranial route and for encephalitis HVEM is largely “irrelevant”." (PMID 22754650, 2012).
Intellectual disability (2 papers, 2014 to 2022). "Furthermore, mutations in NECTIN-1 were shown to be a cause of mental retardation in humans." (PMID 24587018, 2014).
Lymph node metastasis (2 papers, 2023). "Lymph node metastasis was proved to be associated with higher nectin-1 expression (p = 0.007)." (PMID 37568798, 2023). "Nectin-1 expressed in 64 tumors, correlated with lymph node metastasis (N1-2), IIB-IV TNM stage, perineural invasion, tumor location in the pancreatic head and shorter OS." (PMID 37568798, 2023). "In 64 patients, nectin-1 expression in CAF was detected and it was correlated with lymph node metastasis (N1-2), IIB-IV TNM stage, perineural invasion, tumor location in the pancreatic head and, most importantly, with shorter overall survival (OS)." (PMID 37568798, 2023).
microphthalmia (2 papers, 2018 to 2022). Congenital or developmental anomaly in which the eyeballs are abnormally small. "It is interesting that studies on mice lacking nectin-1 or nectin-3 showed a virtually identical ocular phenotype: microphthalmia." (PMID 29342882, 2018). "Studies on mice lacking nectin-1 or nectin-3 showed a virtually identical ocular phenotype: microphthalmia." (PMID 29342882, 2018).
neuropathy (2 papers, 2013 to 2022). A disorder affecting the nervous system that manifests with pain, tingling, numbness, and/or muscle weakness. "Moreover, further studies are required to examine whether the pentraxin-3 and nectin-1 cascade in the spinal dorsal horn is implicated in other pain syndromes, such as inflammatory pain, bone cancer pain, chemotherapy-induced neuropathy and opioid-induced hyperalgesia." (PMID 35625034, 2022). "Since HSV causes nectin-1 downregulation, one may speculate that, in addition to HSV neuropathy, transient decrease of synaptic nectin-1 may affect long term cognitive ability." (PMID 23418609, 2013).
atopic dermatitis (1 paper, 2023). "Costainings with claudin-1 further demonstrated nectin-1 throughout the granular layer with a punctate and reduced pattern of claudin-1 indicative of the strongly redistributed TJ marker in atopic dermatitis epidermis." (PMID 37289055, 2023). "This major AJ component was evenly distributed in the thickened atopic dermatitis epidermis and colocalized with nectin-1 throughout all layers, which was comparable to control skin suggesting that formation of AJs still takes place in the thickened epidermis." (PMID 37289055, 2023). "Taken together, we conclude that access of HSV-1 to its receptor nectin-1 in human skin depends on dysfunctional TJs under pathological conditions such as in atopic dermatitis and in cytokine-treated skin which comprise multiple impaired physical barriers." (PMID 37289055, 2023). "We also found nectin-1 ubiquitously localized in the epidermis of atopic dermatitis and IL-4/IL-13-treated human skin implying that impaired tight-junctions in combination with a defective cornified layer allow the accessibility of nectin-1 to HSV-1." (PMID 37289055, 2023). "Nectin-1 was present throughout all epidermal layers of atopic dermatitis skin; however, its distribution toward the TJ markers ZO-1 and claudin-1 strongly changed suggesting that impaired TJs make nectin-1 more accessible to the virus." (PMID 37289055, 2023). "Nectin-1 distribution in atopic dermatitis skin and in IL-4/IL-13-treated human skin." (PMID 37289055, 2023). "Here, we addressed whether redistribution of the TJ markers influences the presence and distribution of nectin-1, leading to viral entry in lesional atopic dermatitis skin." (PMID 37289055, 2023). "Thus, we cannot dissect the impact of the individual barriers provided by either the stratum corneum or the TJs but suggest that the abnormal cornified layer of atopic dermatitis skin facilitates viral penetration and that only the impaired TJs allow viral access to its receptor nectin-1." (PMID 37289055, 2023). "In contrast, the discontinuous ZO-1 in the granular layer of the thickened atopic dermatitis epidermis no longer localized above nectin-1 and was redistributed to the spinous layer." (PMID 37289055, 2023). "Nectin-1 showed no major redistribution in the thickened atopic dermatitis and IL-4/IL-13-treated human epidermis in which HSV-1 can invade." (PMID 37289055, 2023). "Furthermore, we investigated how inflammation-induced impairment of epidermal barriers can influence the accessibility of nectin-1 for HSV-1 in human skin and whether the facilitated viral invasion in atopic dermatitis skin relies on the redistribution of the receptor." (PMID 37289055, 2023).
bladder urothelial carcinoma (1 paper, 2021). "Univariate analysis showed that histologic grade, T stage, N stage, M stage, TNM stage, FAM83H expression (P < 0.001), and Nectin1 expression (P = 0.002) were significantly associated with the OS of bladder urothelial carcinoma patients." (PMID 34625065, 2021). "Analysis of a publicly available gene expression database revealed a significant correlation between FAM83H and Nectin1 mRNA expression and bladder urothelial carcinoma (BUC)." (PMID 34625065, 2021).
cervical squamous cell carcinoma (1 paper, 2021). A squamous cell carcinoma arising from the cervical epithelium. "However, absent or decreased Nectin1 expression was found in the invading edge of uterine cervical squamous cell carcinomas compared to the center of these tumors." (PMID 34625065, 2021).
co-infection (1 paper, 2014). "Collectively, these data are consistent with the supposition that nectin-1 is required for HSV co-infection-induced chlamydial persistence." (PMID 25414835, 2014). "Additional evidence indicating that nectin-1 plays a critical role in HSV co-infection-induced chlamydial persistence is two-fold." (PMID 25414835, 2014). "Co-infections with nectin-1 specific HSV-1 mutants stimulate chlamydial persistence, as evidenced by aberrant body (AB) formation and decreased production of elementary bodies (EBs)." (PMID 25414835, 2014). "HSV-1 and HSV-2 can drive developing chlamydiae to enter persistence, suggesting that gD interactions with either nectin-1 or HVEM could trigger HSV co-infection-induced persistence." (PMID 25414835, 2014). "Thus, it is possible that by changing nectin-1 expression during co-infection, HSV modulates cellular junction regulation of the cytoskeleton in a manner that has negative downstream effects on chlamydial inclusion stability and development." (PMID 25414835, 2014). "Thus, evidence suggests that, of the known HSV co-receptors, nectin-1 is the most likely candidate involved in HSV co-infection-induced chlamydial persistence." (PMID 25414835, 2014). "To further investigate whether this phenomenon requires viral attachment/entry via nectin-1, we performed co-infections using HSV-1 mutants with altered co-receptor specificity." (PMID 25414835, 2014).
depression (1 paper, 2020). "Nectin-1 has previously been implicated in various neurological and psychiatric disorders, including schizophrenia and depression." (PMID 32413284, 2020).
diabetes (1 paper, 2024). "The interactions between periportal and pericentral hepatocytes, mediated by Fgf, Agt, Nectin1, Vtn, Sema4a, Angpt, Fn1, and Des, were lost in the livers of mice with diabetes at the late-stage." (PMID 39494341, 2024).
erythroleukemia (1 paper, 2019). Acute erythroid leukemia characterised by the presence of at least 50% erythroid precursors and at least 20% myeloblasts in the bone marrow. "To determine the functional contribution of nectin-1 to cytotoxic killing by human NK cells, we first engineered human erythroleukemia K562 cells to express human nectin-1." (PMID 30759143, 2019).
Flavivirus Infections (1 paper, 2024). Infections with viruses of the genus FLAVIVIRUS, family FLAVIVIRIDAE. "Overall, our study has important implications for understanding the entry of BVDV and revealed a novel role for NECTIN1 as a restriction factor that inhibits flavivirus infection." (PMID 39570015, 2024).
hepatoblastoma (1 paper, 2014). Hepatoblastoma (HB) is a malignant hepatic tumor and is the most common pediatric liver cancer. "An important aspect of the current study was the investigation of CD111 (nectin-1) in human hepatoblastoma and renal tumor cell lines and human tumor tissues." (PMID 24497984, 2014). "Finally, these studies showed that the primary entry protein for oHSV, CD111 (nectin-1) was present in human hepatoblastoma and malignant rhabdoid kidney tumor specimens." (PMID 24497984, 2014).
liver cancer (1 paper, 2022). An epithelial or non-epithelial malignant neoplasm that arises from the liver. "In particular, the effects of nectin-1 on the biological characteristics of liver cancer cells were investigated." (PMID 36059705, 2022). "In particular, nectin-1 can promote the proliferation and migration of liver cancer cells and is closely related to different stages and grades of HCC." (PMID 36059705, 2022). "In particular, nectin-1 can promote the proliferation and migration of liver cancer cells and distinguish the prognosis at different stages and grades of HCC." (PMID 36059705, 2022).
Lung Squamous Cell Carcinoma (1 paper, 2025). "NECTIN1, a primary receptor for oncolytic herpes simplex virus, was broadly overexpressed, with particularly high levels observed in Lung Squamous Cell Carcinoma (LUSC) and Cervical Cancer melanoma (CESC)." (PMID 41210942, 2025).
ocular infection (1 paper, 2012). "Our demonstration of the significance of nectin-1 during ocular infection, combined with similar findings using knockout mice, is sure to spark new strategies and the development of novel agents to treat ocular infection." (PMID 23213272, 2012). "However, nectin-1 is the most relevant receptor for ocular infection, since wild-type HSV-1 fails to use nectin-2." (PMID 23213272, 2012).
ovarian tumor (1 paper, 2017). "RT-PCR analysis of matched ascites cells (As), primary ovarian tumor (Ov), and omental metastases (Om) from four patients with high-grade serous ovarian cancer showed that Nectin-1 was expressed in all samples tested in varying amounts." (PMID 28038455, 2017).
Pain (1 paper, 2022). An unpleasant sensory and emotional experience associated with actual or potential tissue damage, or described in terms of such damage. "The effects of pentraxin-3 and nectin-1 on the development of SNL-related neuropathic pain were investigated, and the potential link between pentraxin-3 and nectin-1 was characterized with reference to this pathological condition." (PMID 35625034, 2022).
pancreatic adenocarcinoma (1 paper, 2015). "Most of the pancreatic adenocarcinoma cases demonstrated diffuse nectin-1 (median score: 3.0, mean score: 2.88) and nectin-3 (median score 3.0, mean score: 2.86) expression." (PMID 25690753, 2015).
pancreatic ductal adenocarcinoma (1 paper, 2021). An infiltrating adenocarcinoma that arises from the epithelial cells of the pancreas. "Another study reported that Nectin1 expression in cancer-associated fibroblasts of pancreatic ductal adenocarcinoma was significantly related to invasion, metastasis, and shorter OS." (PMID 34625065, 2021). "Furthermore, Nectin1 expression in cancer-associated fibroblasts was correlated with a poor prognosis in pancreatic ductal adenocarcinoma patients." (PMID 34625065, 2021).
poliovirus infection (1 paper, 2024). An disease or disorder caused by infection with Enterovirus C. "Although NECTIN1 has been previously implicated as a receptor for alpha herpesviruses and a receptor-associated protein in poliovirus infection, our findings reveal a novel role for NECTIN1 in the virus life cycle by influencing BVDV infection dynamics." (PMID 39570015, 2024).
infection (65 papers, 2005 to 2026). The state of being infected such as from the introduction of a foreign agent such as serum, vaccine, antigenic substance or organism. "Infection studies in nectin-1- or HVEM-deficient epidermis identified nectin-1 as the major receptor in murine epidermis, while HVEM has a more limited role." (PMID 37289055, 2023). "Using different cell lines, we and others have shown that the amount of available nectin-1 correlated with susceptibility to infection." (PMID 30759143, 2019). "It has been demonstrated that CHO cells engineered to express human nectin-1 are susceptible to infection via a pH-dependent route whereas CHO cells expressing human paired immunoglobulin-like type 2 receptor alpha (PILRα) are infected via a pH-independent route, possibly by associating with gB." (PMID 33905459, 2021). "Because LUHMES express CADM1/2 and NECTIN1/PVRL1 (Table A1), it is plausible that the measles virus similarly exploits these cell-surface proteins to achieve infection in LUHMES." (PMID 40733616, 2025). "Nectin-1 staining was markedly decreased in foci of infection in the epidermis and in the human keratinocyte HaCaT cell line." (PMID 38857290, 2024). "Consistently, the BVDV NS3 protein expression level was greater in the NECTIN1 knockout cell clones throughout the entire infection course." (PMID 39570015, 2024). "This leads to the enhanced binding of HSV glycoprotein D (gD) to nectin-1 and thus leads to a higher rate of infection." (PMID 39599904, 2024). "Nectin-1 was redistributed, at the protein level, in adjacent uninfected cells surrounding infection, inducible by CCL3, IL-8 (or CXCL8), and possibly CXCL10 and IL-6, thus facilitating spread." (PMID 38857290, 2024). "- Cells expressing Nectin-2 need more HSV particles than Nectin-1 for infection.- Nectin-1 or -2 can mediate HSV-2 entry, but wide-type HSV-1 can interact with nectin-1 only.- The amino acid sequence of Nectin-1 is 30% different from Nectin-2." (PMID 38076455, 2023). "We have successfully engineered suspension, serum-free-adapted CHO cells to express HVEM and/or Nectin-1 proteins, which are necessary for rHSV-1 entry and infection." (PMID 37932360, 2023). "Although there is a drop in nectin-1 following initial infection at 0 h postinfection, the level of surface nectin-1 is similar when treated with CHX." (PMID 35604159, 2022). "In investigating the mechanisms of uptake and infection of both cells we show that expression of the surface receptors, nectin-1 and HVEM are similar, as is the degree of initial uptake." (PMID 33905459, 2021). "This additional feature abrogates the virus ability to enter cells through the natural receptors HVEM/Nectin-1, and enables the specific infection of cells overexpressing ERBB2 in addition to the conditional replication through Survivin/BIRC5 promoter." (PMID 32152425, 2020). "Since saliva stimulation allowed infection of receptor-deficient B78H1 cells, we used neutralizing antibodies against HVEM and nectin-1 to determine if these receptors are used de novo." (PMID 31581238, 2019). "In contrast, infection of control C10 cells (B78H1 cells expressing human nectin-1) yielded multicellular plaques (right)." (PMID 31581238, 2019). "Clearly, further studies of human NK cells, ex vivo and in the context of infection, are needed to define the role of nectin-1, and CD96, in NK cell defense against HSV." (PMID 30759143, 2019). "The earlier studies reported that soluble forms of human and porcine nectin-1 blocked infection of HSV-1 in addition to PRV and BHV-1." (PMID 29342882, 2018). "Female nectin-1+/+ and nectin-1-/- mice were intravaginally infected on day 0 and swabbed every three days until day 21 post infection (pi)." (PMID 27486990, 2016). "In this study, we determined that nectin-1 is required to promote intravaginal infection with C. muridarum in vivo." (PMID 27486990, 2016).